CEP162 (centrosomal protein 162)
Description:
Required to promote assembly of the transition zone in primary cilia. Acts by specifically recognizing and binding the axonemal microtubule. Localizes to the distal ends of centrioles before ciliogenesis and directly binds to axonemal microtubule, thereby promoting and restricting transition zone formation specifically at the cilia base. Required to mediate CEP290 association with microtubules.
Synonyms: C6orf84; KIAA1009; QN1
Tractability: PROTAC: ubiquitination databases record sites on it.
Gene: Protein-coding gene on chromosome 6 (84,124,241 to 84,227,685, reverse strand). Ensembl gene ENSG00000135315.
Subcellular location: Cytoplasm, cytoskeleton, microtubule organizing center, centrosome, centriole; Cytoplasm, cytoskeleton, spindle; Nucleus
Subcellular location (Human Protein Atlas): Cytosol; Nucleoplasm; Basal body; Centriolar satellite; Connecting piece; Mid piece; Principal piece
Pathways (Reactome):
Organelle biogenesis and maintenance: Anchoring of the basal body to the plasma membrane
Gene Ontology:
Molecular function: protein binding
Biological process: cilium assembly
Cellular component: axonemal microtubule; centriole; centrosome; nucleoplasm; cytosol; nucleus; spindle
Genetic constraint (gnomAD): Loss-of-function variants: 58 observed, 65.54 expected, observed/expected ratio (o/e) 0.88, 90% interval 0.71 to 1.1. The upper end of that interval is the gene's LOEUF score, 1.1, which puts it in group 4 of 6, group 1 being the genes least tolerant of losing a copy. Missense variants: 878 observed, 845.46 expected, observed/expected ratio (o/e) 1.04, 90% interval 0.98 to 1.1. Synonymous variants: 301 observed, 288.27 expected, observed/expected ratio (o/e) 1.04, 90% interval 0.95 to 1.15.
Homologues: Orthologues: chimpanzee CEP162 (99% identical), dog CEP162 (84% identical), pig CEP162 (82% identical), rabbit CEP162 (82% identical), mouse Cep162 (75% identical), rat Cep162 (74% identical), guinea pig CEP162 (74% identical), macaque CEP162 (62% identical), tropical clawed frog cep162 (43% identical), zebrafish cep162 (35% identical).
Diseases named in the same sentence as CEP162 in open-access papers:
CEP162 is named in the same sentence as 7 diseases in open-access papers, as found by Europe PMC text mining. Sharing a sentence is not in itself a finding about the gene and the disease. The quoted sentences say what the papers report.
ciliopathy (3 papers, 2023 to 2025). A genetic disorder of the cellular cilia or the cilia anchoring structures, the basal bodies, or of ciliary function. "Loss of CEP162 has been shown to arrest ciliogenesis at the stage of transition zone (TZ) assembly and to cause a ciliopathy phenotype in zebrafish." (PMID 36862503, 2023). "Mutations that disrupt CEP162 microtubule binding would likely result in defective retinal neurogenesis in addition to ciliopathy phenotypes." (PMID 36862503, 2023). "Beyond retinal degeneration and infertility, CEP162 mutations have also been associated with other ciliopathies, including Joubert syndrome, characterized by cerebellar ataxia and intellectual disability, and Meckel–Gruber syndrome, which presents with severe developmental abnormalities." (PMID 40270641, 2025). "Retinal degeneration is one of the most studied ciliopathies associated with CEP162 mutations." (PMID 40270641, 2025). "The diverse clinical manifestations of these ciliopathies highlight the multifaceted role of CEP162 in maintaining ciliary function and cellular homeostasis." (PMID 40270641, 2025). "In summary, the involvement of CEP162 in a range of ciliopathies underscores its critical role in ciliary function and cellular homeostasis." (PMID 40270641, 2025). "Given the critical role of CEP162 in TZ formation, its abnormal expression or function can lead to altered TZ permeability and the development of ciliopathies." (PMID 40270641, 2025). "While Cep131 and Cby have not yet been associated with ciliopathy, mutations in Cep162 and Fam92A have been reported to be linked to human cilia-related diseases." (PMID 38442096, 2024).
retinal degeneration (3 papers, 2019 to 2025). Degeneration of the retina. "In addition to retinal degeneration, CEP162 is also implicated in male infertility through its role in regulating the distribution of microtubule inner proteins (MIPs) in sperm flagella." (PMID 40270641, 2025). "Human retinal degeneration thus resulted from specific loss of the ciliary function of CEP162." (PMID 36862503, 2023). "CEP162 loss halts the ciliogenesis process, specifically the assembly of the connecting cilium stage, which in turn affects protein transport process and resulting in retinal degeneration." (PMID 31130920, 2019). "Abnormal expression or function of CEP162 can lead to altered TZ permeability and disrupted ciliary trafficking, resulting in diseases such as retinal degeneration and infertility." (PMID 40270641, 2025). "CEP162 mutants exhibit retinal degeneration, defective photoreceptor cilia, and impaired sperm motility." (PMID 40270641, 2025). "Truncated CEP162 mutants disrupt TZ assembly, leading to retinal degeneration and infertility." (PMID 40270641, 2025).
retinal ciliopathies (2 papers, 2023 to 2025). "Our genomic, cell-based, and in vivo data show that, although the mitotic function of CEP162 during neuronal development is maintained, specific loss of CEP162 function at the cilium resulted in a novel retinal ciliopathy in humans." (PMID 36862503, 2023). "Thus, specific loss of CEP162 function at the primary cilium is likely the primary cause of the late-onset human retinal ciliopathy." (PMID 36862503, 2023).
polycystic kidney disease (1 paper, 2025). A usually autosomal dominant and less frequently autosomal recessive genetic disorder characterized by the presence of numerous cysts in the kidneys leading to end-stage renal failure. "CEP162 knockout causes embryonic lethality, shortened renal cilia, and polycystic kidney disease." (PMID 40270641, 2025).
retinitis pigmentosa (1 paper, 2023). Retinitis pigmentosa (RP) is an inherited retinal dystrophy leading to progressive loss of the photoreceptors and retinal pigment epithelium and resulting in blindness usually after several decades. "We found that homozygosity for a truncating variant in CEP162, a centrosome and microtubule-associated protein required for transition zone assembly during ciliogenesis and neuronal differentiation in the retina, caused late-onset retinitis pigmentosa in 2 unrelated families." (PMID 36862503, 2023).
CEP162 also shares sentences with these, for which no sentence is quoted: Hydrocephalus (1 paper); Infertility (1).